LINC00665 (long independently transcribed non-coding RNA 665)
Diseases named in the same sentence as LINC00665 in open-access papers (continued):
Sharing a sentence is not in itself a finding about the gene and the disease.
hepatocellular carcinoma (20 papers, 2019 to 2024). A malignant tumor that arises from hepatocytes. "High expression of LINC00665 has potential diagnostic value in breast, gastric and hepatocellular carcinoma." (PMID 35563845, 2022). "LINC00665 is highly expressed in hepatocellular carcinoma and associated to the prognosis, and may participate in cell cycle regulation according to the results of bioinformatics and clinical sample analysis." (PMID 35152838, 2022). "In 2018, LINC00665 was initially identified as a lncRNA, which is highly overexpressed in hepatocellular carcinoma (HCC) and associated with poor progression in HCC patients." (PMID 34277412, 2021). "For example, LINC00665 exerted an important pro-inflammatory role by activating the NF-κB pathway in hepatocellular carcinoma." (PMID 39219375, 2024). "In hepatocellular carcinoma, high expression of LINC00665 points to larger tumor size and more severe vascular invasion." (PMID 35563845, 2022). "In digestive system tumors, the LINC00665/miR-186-5p/MAP4K3 axis and the LINC00665/miR-424-5p/BCL9L axis promote the progression of hepatocellular carcinoma and cholangiocarcinoma, respectively." (PMID 35563845, 2022). "In hepatocellular carcinoma, LINC00665 modulates viability, apoptosis, and autophagy through sponging miR-186-5p and regulating MAP4K3." (PMID 33407473, 2021). "LINC00665, a novel lncRNA, has been found to be overexpressed in hepatocellular carcinoma (HCC), and patients with LINC00665 high expression had a worse overall survival rate." (PMID 34232917, 2021). "For example, in hepatocellular carcinoma, LINC00665 expression is remarkably upregulated, and its knockdown inhibits cancer cell viability and induces apoptosis and autophagy by binding miR-186-5p." (PMID 32983239, 2020). "It has been reported that LINC00665 increases the malignancy of hepatocellular carcinoma by activating the protein kinase R (PKR)/nuclear factor (NF)-κB pathway and induce gastric cancer progression by activating the Wnt signaling pathway." (PMID 32793593, 2020). "Role of LINC00665 in hepatocellular carcinoma, glioma, melanoma, gastric cancer, and lung cancer." (PMID 36429005, 2022). "In hepatocellular carcinoma, LINC00665 can differentiate between normal and tumor tissues." (PMID 35563845, 2022). "Another study in hepatocellular carcinoma cells has shown that LINC00665 silencing could decrease proliferation, migration, and invasion, whereas up-regulation the CIP2A-BP micropeptide enhances these features." (PMID 36429005, 2022). "Previous studies have established that LINC00665 acts as an oncogenic molecule in multiple human cancers, such as breast cancer, gastric cancer, hepatocellular carcinoma, prostate cancer, osteosarcoma, colorectal cancer, myeloma, glioma, ovarian cancer, and NSCLC." (PMID 34277412, 2021). "In hepatocellular carcinoma, LINC00665 regulates cell cycle pathways, whereas in lung adenocarcinoma, it acts as a ceRNA and binds miR-98, subsequently activating the aldo–keto reductase family 1 member B10 (AKR1B10)–extracellular-signal-regulated kinase (ERK)-signaling pathway." (PMID 32983239, 2020). "Bioinformatics analysis using public databases also suggested that linc00665 overexpression in hepatocellular carcinoma might facilitate cancer progression by regulating cell cycle pathways." (PMID 30692511, 2019). "LINC00665 is upregulated in HGSOC, it is also overexpressed in hepatocellular carcinoma (HCC) and lung cancer patients, but act as an oncogene with poor prognosis, which is contrary to our univariate Cox regression analysis (HR:0.89, 95% CI [0.73–1.1])." (PMID 32419983, 2020). "LINC00665 can modulate 11 mRNAs by regulating m6A enzymes YTHDF1, IGF2BP1, and IGF2BP2 in hepatocellular carcinoma (HCC)." (PMID 38351139, 2024).
hepatocellular carcinoma (continued). "Also, LINC00665 was proven to display high expression in hepatocellular carcinoma cells and tissues, and could facilitate cell viability and autophagy while suppressing cell apoptosis via miR-186-5p/MAP4K3 axis in hepatocellular carcinoma." (PMID 35101035, 2022).
glioma (14 papers, 2020 to 2023). A benign or malignant brain and spinal cord tumor that arises from glial cells (astrocytes, oligodendrocytes, ependymal cells). "Silencing LINC00665, which is associated with poor prognosis in gliomas, suppressed the expression of markers of EMT." (PMID 36090045, 2022). "Herein, nine ferroptosis-related lncRNAs (AC062021.1, FAM66C, MIR497HG, TMEM72-AS1, AC010729.2, FAM225B, HOXA-AS2, LINC00662, and LINC00665) were identified to construct a risk model in patients with glioma." (PMID 35174152, 2022). "Through lncRNA microarray analysis, LINC00665 was identified to be differentially expressed in glioma." (PMID 35664776, 2022). "In fact, apart from a single study on glioma, other studies have consistently demonstrated that LINC00665 facilitates proliferation and malignant behaviors of cancer cells." (PMID 36429005, 2022). "In glioma, there are two opposing insights into the aberrant expression and mechanism of action of LINC00665." (PMID 35563845, 2022). "In nervous system tumors, LINC00665 was found to be positively correlated with the malignant pathological grade of glioma." (PMID 35563845, 2022). "Taken together, the TAF15/LINC00665/MTF1(YY2)/GTSE1 axis has been acknowledged as an important axis in the modulation of the malignant features of glioma cells." (PMID 36429005, 2022). "One view is the same as mainstream studies, that LINC00665 is upregulated as an oncogenic factor and promotes glioma progression through a ceRNA mechanism (LINC00665/miR-34a-5p/AGTR1)." (PMID 35563845, 2022). "LINC00665 promoted MTF1 degradation, and MTF1 bound to the promoter region of GTSE1 and transcription promoted GTSE1 expression, which proved that LINC00665/MTF1/GTSE1 axis played an important role in regulating the biological behavior of glioma cells." (PMID 36110851, 2022). "Current studies suggest that LINC00665 is upregulated as an oncogene in most cancers, but some studies have found that in triple-negative breast cancer and glioma, LINC00665 can be downregulated as a tumor suppressor." (PMID 35563845, 2022). "The PABPC1-BDNF-AS-RAX2-DLG5 axis was shown to play the same role as the TAF15/LINC00665/MTF1(YY2)/GTSE1 axis in regulating the biological behavior of gliomas." (PMID 34178684, 2021). "In glioma, LINC00665 is downregulated in patient samples and cell lines, and overexpression of LINC00665 is associated with inhibiting malignant behaviors of glioma cells." (PMID 33436545, 2021). "LINC00665 exhibits increased expression in human glioma cell lines and tissues." (PMID 37403043, 2023). "The forest plot shows that EPB41L4A.AS1, GDNF.AS1, HAR1A, LINC00237, SLC25A21.AS1, SNA13.AS1, and WDFY3.AS2 are the protective factors with HR < 1, while LINC00092, LINC00265, LINC00339, LINC00665, PAXIP1.AS2, SNHG16, SNHG9 and SOCS2.AS1 are risk factors with HR>1 in glioma patients." (PMID 35273128, 2022). "In addition, qRT-PCR results showed that LINC00665 was distributed in the cytoplasm fraction of glioma cells." (PMID 35356290, 2022). "These small differences may contribute to the divergence of LINC00665 expression in gliomas." (PMID 35563845, 2022). "Furthermore, in gliomas, aberrant expression of LINC00665 has two opposing observations." (PMID 35563845, 2022). "Additionally, the TAF15/LINC00665/MTF1(YY2)/GTSE1 axis is crucial for regulating the malignant biological behaviors of glioma cells, which might help in the development of a novel therapeutic strategy for human glioma." (PMID 34178684, 2021). "Consistent with previous research findings, the other 7 lncRNAs that we have identified in our risk model, have all been reported to play significant biological roles in gliomas, particularly HOXA-AS3, LINC00665, MIR155HG, and NEAT1." (PMID 37403043, 2023). "CRNDE showed low expression in WHO grade II samples, while the expression of LINC00665 and NEAT1 remained stable across glioma grades in the CGGA cohorts." (PMID 36090045, 2022).
glioma (continued). "Results show the mean expression levels of LINC00665, LINC00339, SNHG16, PAXIPI.AS2 and LINC00092 in the glioma tissues are higher than those in the NBTs." (PMID 35273128, 2022). "For example, LINC00665 is downregulated in glioma and mediates STAU1-mediated MTF1 and YY2 stability, affecting malignant biological behavior of glioma." (PMID 32851059, 2020). "Additionally, overexpression of TAF15 stabilizes LINC00665, leading to reduced STAU1-mediated mRNA degradation of both MTF1 and YY2, thereby restricting GTSE1 transcription and ultimately disrupting glioma’s malignant progression." (PMID 37403043, 2023). "In glioma, the TAF15|LINC00665/MTF1|YY2/GTSE1 axis inhibits malignant tumor progression.TATA-box-binding protein-associated factor 15 (TAF15) is a member of the FET family and plays an important role in regulating mRNA transcription, RNA splicing, and trafficking." (PMID 35563845, 2022). "However, another view is that LINC00665 can act as a protective factor for glioma, inhibiting the malignant development of the tumor through the TAF15|LINC00665/MTF1|YY2/GTSE1 axis." (PMID 35563845, 2022). "Although there is evidence demonstrating that LINC00665 inhibits glioma progression via STAU1-mediated mRNA degradation, another experiment highlights that fact that LINC00665 overexpression is responsible for reduced overall survival of prostate cancer patients." (PMID 35773731, 2022). "In glioma cells, in vitro experiments have indicated down-regulation of TAF15 and LINC00665." (PMID 36429005, 2022).
gastric cancer (10 papers, 2020 to 2025). A primary or metastatic malignant neoplasm involving the stomach. "Functionally, FBXO18-AS and LINC00665 promote gastric cancer cell proliferation, migration, invasion, and EMT." (PMID 41437175, 2025). "In gastric cancer, LINC00665 expression is related to cancer staging and poor prognosis, and accelerates cell proliferation and invasion by binding miR-149-3p." (PMID 32983239, 2020). "In gastric cancer, LINC00665 was positively correlated with the depth of tumor invasion." (PMID 35563845, 2022). "LINC00665 can promote tumorigenesis of gastric cancer via regulating miR-149-3p and RNF2." (PMID 33407473, 2021). "In gastric cancer, RNF2 and GRP78 are upregulated through the LINC00665/miR-149-3p axis and LINC00665/miR-379-5p axis, respectively, to promote gastric cancer progression." (PMID 35563845, 2022). "A study in gastric cancer found that silencing of LINC00665 can downregulate the expression levels of TGF-β and its downstream factors Smad-2 and α-SMA, indicating that LINC00665 may promote the progression of EMT in gastric cancer through the TGF-β/Smad-2 signaling pathway." (PMID 35563845, 2022).
lung carcinoma (10 papers, 2020 to 2024). "Elevated expression of LINC00665 has been shown in lung cancer tissues and is associated with TNM staging, lymph node metastasis, and tumor size." (PMID 38951802, 2024). "To investigate whether LINC00665 is associated with lung cancer metastasis and immune escape, we collected tumor tissues and corresponding adjacent tissues from 84 lung cancer patients." (PMID 38951802, 2024). "qRT-PCR results demonstrated a significant reduction in LINC00665 expression in lung cancer cells in the sh-LINC00665 group compared to the sh-NC group (all P < 0.001), indicating successful cell transfection." (PMID 38951802, 2024). "The results showed that overexpression of HHLA2 partially reversed the inhibitory effects of LINC00665 knockdown on the proliferation, migration, invasion, and promotion of apoptosis in lung cancer cells (all P < 0.05)." (PMID 38951802, 2024). "LINC00665 knockdown significantly inhibited lung cancer cell growth and metastasis, promoting sensitivity to NK cells." (PMID 38951802, 2024). "The results showed that LINC00665 knockdown significantly inhibited the proliferation of lung cancer cells compared to the sh-NC group (all P < 0.01)." (PMID 38951802, 2024). "The impact of LINC00665 on lung cancer behavior was further elucidated through in vitro experiments." (PMID 38951802, 2024). "Of note, the involvement of oncogenic LINC00665 in the progression of lung cancers has previously been documented; the suppression of LINC00665 restricts malignant phenotypes of NSCLC cells via modulating a miRNA-dependent signaling." (PMID 35918714, 2022). "Compared with normal lung tissues, miR-138-5p expression in lung cancer tissues was relatively low, and the expression of miR-138-5p and LINC00665 were significantly negatively correlated." (PMID 35356290, 2022). "LINC00665 triggers lung carcinoma progression by sponging miR-98 and thus mediates the ERK signaling." (PMID 33613764, 2021). "We have successfully constructed a silencing plasmid for LINC00665 and plan to investigate the tumor biology effect of the intervention of LINC00665 on lung cancer cells." (PMID 33627711, 2021). "It is reported that LINC00665 is upregulated in lung carcinoma cases and correlated to a poor prognosis." (PMID 33613764, 2021). "Furthermore, we explored the downstream regulatory mechanism of LINC00665 in the modulation of malignant behaviors in lung cancer cells and the cytotoxicity of NK cells." (PMID 38951802, 2024). "In addition, microarray profiling suggested that LINC00665 was differentially expressed in radioresistant samples relative to radiosensitive samples in lung cancer." (PMID 35918714, 2022). "Meanwhile, in the in vitro transwell migration assay, the knockdown of LINC00665 significantly inhibited the migration of NK cells (all P < 0.001), indicating that LINC00665-silenced lung cancer cells may inhibit the infiltration of NK cells into lung cancer tumors." (PMID 38951802, 2024). "Furthermore, they also demonstrated that the transcription factor SP1 could bind to the promoter of LINC00665 and partly upregulate the transcription of LINC00665 in lung cancer cells." (PMID 35356290, 2022). "We performed cell transfection to simultaneously knock down LINC00665 and overexpress HHLA2 in lung cancer cells (both P < 0.05) and examined their impact on the malignant behavior of lung cancer cells." (PMID 38951802, 2024). "In conclusion, our study unravels a novel regulatory network involving LINC00665, TCF7, HHLA2, and immune escape in lung cancer." (PMID 38951802, 2024). "Western blot results demonstrated that knocking down LINC00665 or TCF7 (all P < 0.001) significantly decreased the expression of HHLA2 in lung cancer cells (all P < 0.05)." (PMID 38951802, 2024). "LINC00665, through recruitment of TCF7 and upregulation of HHLA2, inhibits NK cell cytotoxicity, promoting the development and immune evasion of lung cancer." (PMID 38951802, 2024).
lung carcinoma (continued). "Abnormal expression of Long Intergenic Non-Protein Coding RNA 665 (LINC00665) exists in a variety of tumors, including liver cancer, gastric cancer and lung cancer." (PMID 35152838, 2022). "Based on these analyses, we hypothesize that LINC00665 may promote the transcription of HHLA2 in lung cancer cells by recruiting transcription factor TCF7, thereby inhibiting NK cell cytotoxicity and promoting immune escape and the development of lung cancer." (PMID 38951802, 2024). "However, the biological role of LINC00665 in immune escape in lung cancer remains unclear, and there are currently no reported studies on this aspect." (PMID 38951802, 2024). "However, there is currently no research reporting whether LINC00665 can promote the expression of HHLA2 in lung cancer cells and inhibit NK cell cytotoxicity by targeting binding TCF7, leading to immune escape and the development of lung cancer." (PMID 38951802, 2024). "LINC00665, TCF7 mRNA, and HHLA2 mRNA expression levels were significantly higher in lung cancer tissues than adjacent tissues, with non-metastatic lung cancer showing higher expression than metastatic lung cancer." (PMID 38951802, 2024).
lung adenocarcinoma (7 papers, 2020 to 2024). A carcinoma that arises from the lung and is characterized by the presence of malignant glandular epithelial cells. "The expression of LINC00665 is increased in lung adenocarcinoma, and LINC00665 upregulation is associated with poor outcome in patients with lung adenocarcinoma." (PMID 31907362, 2020). "LINC00665, as revealed by our analyses, exhibits elevated expression in both lung adenocarcinoma (LUAD) and lung squamous cell carcinoma (LUSC) patients, correlating with adverse prognosis." (PMID 38951802, 2024). "In respiratory tumors, upregulated LINC00665 was significantly associated with larger tumors, advanced TNM stage, and lymph node metastasis in non-small cell lung cancer and lung adenocarcinoma." (PMID 35563845, 2022). "In lung adenocarcinoma tissues, the expression of LINC00665 is closely related to the aggressive clinicopathological characteristics of patients and can be used as an independent predictor of relapse-free survival." (PMID 35233461, 2022). "For example, LINC00665 is significantly upregulated in lung adenocarcinoma pateints and predicted poor prognosis, while enforcing LINC00665 expression promotes proliferation and metastasis of lung adenocarcinoma cells by acting as ceRNA for miR-98 and subsequently activating ERK signaling." (PMID 33436545, 2021).
prostate carcinoma (7 papers, 2021 to 2024). A carcinoma that arises from epithelial cells of the prostate gland. "In addition, they performed the Kaplan-Meier survival analysis and found that the high LINC00665 expression level was associated with the poor survival of prostate cancer patients." (PMID 35356290, 2022). "Therefore, LINC00665 possesses a tumor-promoting role of prostate cancer and can be considered as a prognostic and diagnostic tool." (PMID 35773731, 2022). "Association of LINC00665 expression with clinicopathologic characteristics of prostate cancer." (PMID 34094920, 2021). "In prostate cancer, LINC00665 can interact with EZH2 and LSD1, recruiting them to the KLF2 promoter to repress its transcription, thereby promoting the malignant progression of cancer." (PMID 35563845, 2022). "This study aimed to explore the function of LINC00665 on the proliferation and metastasis of prostate cancer (PCa), and the potential regulatory mechanisms were also investigated." (PMID 34094920, 2021). "Experiment in xengraft models of breast, colorectal, gastric, liver, lung, and prostate cancers as well as cholangiocarcinoma, endometrial carcinoma, and melanoma have confirmed that up-regulation of LINC00665 increases tumor burden, while its silencing decreases tumor weight." (PMID 36429005, 2022). "Furthermore, experiments have shown that LINC00665 knockdown inhibited the proliferation, migration, and invasion of prostate cancer cells." (PMID 35356290, 2022). "LINC00665 can upregulate SND1 and RRAGD by sponging miR-1224-5p and miR-449b-5p, and promote the progression of prostate cancer and high-grade serous ovarian cancer, respectively." (PMID 35563845, 2022).